ENSG00000296790 (novel transcript, antisense to COL8A1)
Gene: Long non-coding RNA gene on chromosome 3 (99,676,295 to 99,817,818, reverse strand). Ensembl gene ENSG00000296790.
Gene Ontology:
Biological process: SRP-dependent cotranslational protein targeting to membrane, signal sequence recognition
Cellular component: signal recognition particle, endoplasmic reticulum targeting